EFR3A (EFR3 homolog A)
Description:
Component of a complex required to localize phosphatidylinositol 4-kinase (PI4K) to the plasma membrane. The complex acts as a regulator of phosphatidylinositol 4-phosphate (PtdIns(4)P) synthesis (Probable). In the complex, EFR3A probably acts as the membrane-anchoring component. Also involved in responsiveness to G protein-coupled receptors; it is however unclear whether this role is direct or indirect.
Synonyms: KIAA0143
Tractability: Antibody: UniProt places it where antibodies can reach, with high confidence; its Gene Ontology location is reachable by antibodies, with high confidence; the Human Protein Atlas places it where antibodies can reach. PROTAC: ubiquitination databases record sites on it; its protein half-life has been measured.
Gene: Protein-coding gene on chromosome 8 (131,904,077 to 132,013,642, forward strand). Ensembl gene ENSG00000132294.
Subcellular location: Cell membrane; Cytoplasm, cytosol
Subcellular location (Human Protein Atlas): Cytosol; Plasma membrane
Gene Ontology:
Biological process: protein localization to plasma membrane; phosphatidylinositol phosphate biosynthetic process; synaptic vesicle priming
Cellular component: cytosol; plasma membrane; glutamatergic synapse; presynapse
Genetic constraint (gnomAD): Loss-of-function variants: 52 observed, 67.77 expected, observed/expected ratio (o/e) 0.77, 90% interval 0.61 to 0.97. The upper end of that interval is the gene's LOEUF score, 0.97, which puts it in group 4 of 6, group 1 being the genes least tolerant of losing a copy. Missense variants: 759 observed, 770.54 expected, observed/expected ratio (o/e) 0.99, 90% interval 0.93 to 1.05. Synonymous variants: 262 observed, 253.99 expected, observed/expected ratio (o/e) 1.03, 90% interval 0.93 to 1.14.
Homologues: Orthologues: chimpanzee EFR3A (99% identical), macaque EFR3A (99% identical), dog EFR3A (98% identical), rabbit EFR3A (97% identical), rat Efr3a (97% identical), mouse Efr3a (97% identical), guinea pig EFR3A (96% identical), pig EFR3A (95% identical), tropical clawed frog efr3a (87% identical), zebrafish efr3a (73% identical), Caenorhabditis elegans efr-3 (39% identical), Drosophila melanogaster stmA (38% identical). Paralogues in human: EFR3B (63% identical).
Diseases named in the same sentence as EFR3A in open-access papers:
EFR3A is named in the same sentence as 24 diseases in open-access papers, as found by Europe PMC text mining. Sharing a sentence is not in itself a finding about the gene and the disease. The quoted sentences say what the papers report.
autism (4 papers, 2014 to 2024). Persistent deficits in social interaction and communication and interaction as well as a markedly restricted repertoire of activity and interest as well as repetitive patterns of behavior. "Relevant to neurological diseases, rare variants in EFR3A have been shown to cause autism and knockout of the gene causes spiral ganglion neurons to degenerate in mouse models." (PMID 38641715, 2024). "For example, a loss of KDM5B binding was found at the promoter of a candidate autism-risk gene, EFR3A." (PMID 27525107, 2016). "We also compared the expression profile of EFR3A with a discrete module of co-expressed genes (M12) significantly associated with ASD in a prior transcriptome analysis of post-mortem autism and control brains." (PMID 24860643, 2014).
pancreatic cancer (3 papers, 2021 to 2025). "This interaction was considered important for tumorigenesis of pancreatic cancer, i.e., loss of EFR3A inhibited KRAS signaling and cancer progression." (PMID 37880612, 2023). "Interestingly while components of the EFR3A complex were upregulated in KRAS mutation-positive pancreatic tumors, we nevertheless show synergy of C7 with sotorasib in KRASG12C-mutant human lung adenocarcinoma cell lines." (PMID 34504076, 2021). "Human EFR3A and EFR3B also regulate KRAS signalling at the plasma membrane in pancreatic cancer cells." (PMID 39991135, 2025).
Alzheimer disease (2 papers, 2025). A progressive, neurodegenerative disease characterized by loss of function and death of nerve cells in several areas of the brain leading to loss of cognitive function such as memory and language. "Interestingly, EFR3A is associated with the development of Alzheimer’s disease." (PMID 40136694, 2025). "Other studies indicate a potential role of EFR3A in the development of Alzheimer’s disease." (PMID 40305161, 2025). "Moreover, selectively deleting Efr3a at the presynaptic site in CA1 pyramidal neurons leads to improved cognitive function and memory in the APP/PS1 mice model of Alzheimer’s disease." (PMID 40136694, 2025).
autism spectrum disorder (2 papers, 2014 to 2026). A spectrum of developmental disorders that includes autism, and Asperger syndrome. "Whole-exome sequencing studies in autism spectrum disorder (ASD) have identified de novo mutations in novel candidate genes, including the synaptic gene Eighty-five Requiring 3A (EFR3A)." (PMID 24860643, 2014).
colorectal cancer (2 papers, 2025). A primary or metastatic malignant neoplasm that affects the colon or rectum. "The first mention of the possible link between EFR3A and cancer appeared in the work by Zhou, who investigated somatic genetic changes accumulating during the progression of colorectal adenoma to colorectal carcinoma (CRC)." (PMID 40305161, 2025).
glioma (2 papers, 2025). A benign or malignant brain and spinal cord tumor that arises from glial cells (astrocytes, oligodendrocytes, ependymal cells). "In this brief review, we summarize available information linking EFR3A to human disease states including autism, glioma, cardiovascular diseases, and colorectal and pancreatic cancer." (PMID 40305161, 2025). "EFR3A was found among the fourteen genes as the features of primary glioma, allowing the stratification of these patients into low- and high-risk groups." (PMID 40136694, 2025). "The study which utilized the data from the CRISPR-Cas9 lethality screens performed on patient-derived glioma stem cells indicated a dependency on EFR3A at least in a single mesenchymal GSC-0131 line." (PMID 40136694, 2025).
adenoma (1 paper, 2025). A neoplasm arising from the epithelium. "The signature of adenoma included a novel missense variant in the EFR3A gene (chr8: 133057465; p.G390E), which was not further found in the validation cohort of 288 CRC cases (non-recurrent mutation)." (PMID 40305161, 2025). "It is unclear whether the EFR3A variant represented a rare, non-significant mutation event in the adenoma or if it was overlooked by Sanger sequencing due to its low frequency." (PMID 40305161, 2025).
brain tumors (1 paper, 2025). "Data on the importance of EFR3A and its product in neoplastic diseases concern colorectal, pancreatic ductal, nasopharyngeal carcinomas, and brain tumors." (PMID 40136694, 2025).
coronary artery disease (1 paper, 2025). "The study by Sun and collaborators revealed increased levels of EFR3A mRNA in the plasma of 60 patients diagnosed with coronary artery disease." (PMID 40305161, 2025).
epilepsy (1 paper, 2025). A brain disorder characterized by episodes of abnormally increased neuronal discharge resulting in transient episodes of sensory or motor neurological dysfunction, or psychic dysfunction. "A better understanding of the EFR3A gene in epilepsy requires further studies, but taking into account that the pathogenesis of epilepsy is associated with calcium-related pathways and synaptic signaling, the EFR3A gene could be a good candidate for further studies." (PMID 40305161, 2025).
glioblastoma (1 paper, 2025). The most malignant astrocytic tumor (WHO grade IV). "In vitro, validation experiments performed on glioblastoma cell line GSC-0827 expressing high levels of EFR3B (EFR3Bhigh) and glioblastoma GSC-0131 cell line with trace expression of EFR3B (EFR3Blow) confirmed the compensatory relationship between EFR3A and EFR3B." (PMID 40305161, 2025).
hearing loss (1 paper, 2017). "Efr3a KD temporarily suppressed the rapid loss of hearing ability, and the progressive and relatively slower degenerative alterations in SGNs in the model of hearing loss, indicating Efr3a KD produced a beneficial effect against the neurodegeneration of SGNs induced by aminoglycoside antibiotics." (PMID 28424585, 2017).
liver cancer (1 paper, 2021). An epithelial or non-epithelial malignant neoplasm that arises from the liver. "Across all human cancers (n = 10,967 samples) there was a general bias towards EFR3A amplification, with ovarian, esophageal, breast, pancreatic, and liver cancers all exhibiting over 10% gene amplification." (PMID 34504076, 2021).
myocardial infarction (1 paper, 2021). Gross necrosis of the myocardium, as a result of interruption of the blood supply to the area, as in coronary thrombosis. "However, EFR3A showed significantly decreased expression in the left ventricular remodeling in swine after myocardial infarction cardiac by analyzing the GEO database GSE27962 (P = 6.94 × 10−4)." (PMID 34158603, 2021).
pancreatic adenocarcinoma (1 paper, 2021). "In sum, the EFR3A complex appears to be preferentially upregulated in KRAS-mutant pancreatic adenocarcinoma, which is associated with a worse clinical outcome." (PMID 34504076, 2021). "As above, we validated these results in 3D-transformed growth, again finding that loss of EFR3A, EFR3B, or both reduced colony formation of all four pancreatic adenocarcinoma cells in soft agar." (PMID 34504076, 2021). "In sum, loss of EFR3A (and/or EFR3B) expression inhibits oncogenic signaling in human KRAS-mutant pancreatic adenocarcinoma cells, which manifests as a reduction in transformed and tumorigenic growth." (PMID 34504076, 2021). "We find that pancreatic adenocarcinoma patients with an EFR3A genomic alteration (almost exclusively gene amplification) have a 26% reduction in overall median survival compared to patients without an EFR3A genomic alteration (i.e. 15.3 versus 20.8 months)." (PMID 34504076, 2021). "Finally, comparing the survival of pancreatic adenocarcinoma patients with high (n = 44) versus low (n = 46) EFR3A mRNA levels from the TGCA database revealed a 29% reduction in overall median survival of the former." (PMID 34504076, 2021). "To evaluate the role of endogenous EFR3A in a cancer driven by an oncogenic mutation in the native KRAS gene, we targeted EFR3A, EFR3B, or both genes by CRISPR/Cas9-mediated gene inactivation as above in the KRAS-mutant human pancreatic adenocarcinoma cell line HPAF-II47." (PMID 34504076, 2021). "Furthermore, loss of EFR3A, EFR3B, or both reduced tumor growth of a human pancreatic adenocarcinoma cell line in vivo." (PMID 34504076, 2021). "Although a limited number of samples, differentiating KRAS mutation-positive (n = 64) from KRAS mutation-negative (n = 115) pancreatic adenocarcinoma samples revealed higher EFR3A expression in the former." (PMID 34504076, 2021). "EFR3A gene amplification also tracked with KRAS-mutant pancreatic adenocarcinoma samples." (PMID 34504076, 2021). "At the gene expression level, GEPIA analysis of the PAAD cancer dataset revealed a significant 95% increase in relative EFR3A mRNA level in pancreatic adenocarcinoma tumors (n = 179) compared to matched normal (n = 171) tissues." (PMID 34504076, 2021). "Comparing EFR3A gene amplification in examples of cancers driven by a specific RAS isoform, we find EFR3A gene amplification is highest in pancreatic adenocarcinoma." (PMID 34504076, 2021). "Interestingly, components of EFR3A signaling are upregulated in human pancreatic adenocarcinoma, but not other tested RAS-mutant (KRAS, NRAS, or HRAS) cancers." (PMID 34504076, 2021).
cancer (5 papers, 2021 to 2025). A tumor composed of atypical neoplastic, often pleomorphic cells that invade other tissues. "An increasing number of studies have identified significant correlations between mutational and expressional abnormalities in EFR3A and various human diseases, including neurological disorders, cardiovascular conditions, and cancer." (PMID 40305161, 2025). "Given that miR-367 is dysregulated in numerous pathologies associated with chronic inflammation, including cancer, dementia, stroke, and diabetes, the expression of EFR3A may also be susceptible to changes in these conditions." (PMID 40305161, 2025). "This review aims to summarize the diverse roles of EFR3A in various human pathologies, including neurological disorders, cardiovascular diseases, and cancer." (PMID 40305161, 2025). "To explore EFR3A in the context of human cancers we surveyed the cBioportal cancer genomics datasets for genomic alterations in the EFR3A gene." (PMID 34504076, 2021). "The importance of the EFR3A’s apparent role as a resting state raft organizing protein could have implications for human health, in particular human cancer biology." (PMID 37880612, 2023). "Analysis of the spectrum of genetic alterations in EFR3A across all human cancers (cBioportal cancer genomics datasets, n = 10,967 samples in total) revealed that PDAC exhibits the highest EFR3A amplification (almost 12% of cases) among all neoplasms." (PMID 40305161, 2025). "The finding that EFR3A recruits PI4KA and binds oncogenic KRAS suggests the possibility of targeting this signaling circuit at the level of the kinase for the treatment of KRAS-mutant cancers." (PMID 34504076, 2021).
neoplasm (4 papers, 2021 to 2025). A benign or malignant tissue growth resulting from uncontrolled cell proliferation. "Further basic research is needed to clarify the potential clinical applications of EFR3A/EFR3A, whether as a biomarker for certain diseases or as a therapeutic target, particularly in gene therapy for specific neoplasms." (PMID 40305161, 2025). "We show that this reduction in tumor growth was, as in 2D- and 3D-transformed growth assays, associated with a reduction in oncogenic KRAS signaling, namely we observed a reduction in P-ERK and P-AKT levels in tumors in which EFR3A, EFR3B, or both genes were inactivated." (PMID 34504076, 2021).
neurological diseases (3 papers, 2024 to 2025). "EFR3A was also found to be engaged in essential tremor (ET), a common neurological disorder." (PMID 40136694, 2025). "Neurological disorders include autism spectrum disorders (ASD), in which six somatic, nonsynonymous mutations in the EFR3A coding sequence were observed twice more frequently in patients than in control subjects, as was found in a large cohort exome and Sanger sequencing-based study." (PMID 40136694, 2025).
cardiovascular diseases (2 papers, 2025). "This brief review summarizes the current knowledge regarding the potential roles of EFR3A in human disease states, including neurological and cardiovascular disorders, as well as various neoplasia-based diseases." (PMID 40305161, 2025). "There are also reports linking EFR3A with cardiovascular diseases, in particular with coronary artery disease (CAD), as EFR3A was found to be one of three genes regulated by miR-367." (PMID 40136694, 2025).
EFR3A also shares sentences with these, for which no sentence is quoted: colorectal adenoma (2 papers); lung adenocarcinoma (1); nasopharyngeal carcinoma (1); nonsmall cell lung cancer (1); pancreatic ductal adenocarcinoma (1).